SPATA24 (spermatogenesis associated 24)
Description:
Binds DNA with high affinity but does not bind to TATA boxes. Synergises with GMNN and TBP in activation of TATA box-containing promoters and with GMNN and TBPL1 in activation of the NF1 TATA-less promoter. May play a role in cytoplasm movement and removal during spermiogenesis (By similarity).
Synonyms: T6441; CCDC161
Tractability: PROTAC: ubiquitination databases record sites on it.
Gene: Protein-coding gene on chromosome 5 (139,396,563 to 139,404,089, reverse strand). Ensembl gene ENSG00000170469.
Subcellular location: Cytoplasm; Nucleus, nucleolus; Nucleus, nucleoplasm
Subcellular location (Human Protein Atlas): Cytosol; Nucleoplasm
Gene Ontology:
Molecular function: protein binding; DNA binding; identical protein binding
Cellular component: cytosol; nucleoplasm; cytoplasm; nucleus; nucleolus
Genetic constraint (gnomAD): Loss-of-function variants: 22 observed, 30.17 expected, observed/expected ratio (o/e) 0.73, 90% interval 0.52 to 1.04. The upper end of that interval is the gene's LOEUF score, 1.04, which puts it in group 4 of 6, group 1 being the genes least tolerant of losing a copy. Missense variants: 215 observed, 254.61 expected, observed/expected ratio (o/e) 0.84, 90% interval 0.75 to 0.94. Synonymous variants: 76 observed, 94.64 expected, observed/expected ratio (o/e) 0.8, 90% interval 0.67 to 0.97.
Homologues: Orthologues: macaque SPATA24 (99% identical), pig SPATA24 (96% identical), rabbit SPATA24 (94% identical), dog SPATA24 (93% identical), mouse Spata24 (91% identical), guinea pig SPATA24 (87% identical), rat Spata24 (82% identical).
Diseases named in the same sentence as SPATA24 in open-access papers:
SPATA24 is named in the same sentence as 1 disease in open-access papers, as found by Europe PMC text mining. Sharing a sentence is not in itself a finding about the gene and the disease.
SPATA24 shares sentences with these, for which no sentence is quoted: Obesity (1 paper).